Y_RNA (Y RNA )
Gene: Miscellaneous RNA gene on chromosome 8 (96,309,221 to 96,309,322, reverse strand). Ensembl gene ENSG00000199732.
Homologues: Orthologues: chimpanzee Y_RNA (97% identical), macaque Y_RNA (90% identical). Paralogues in human: Y_RNA (90% identical), RNY3 (89% identical), Y_RNA (89% identical), RNY3P1 (88% identical), RNY3P14 (88% identical), Y_RNA (88% identical), Y_RNA (87% identical), RNY3P7 (86% identical), Y_RNA (86% identical), Y_RNA (85% identical), Y_RNA (84% identical), RNY3P11 (83% identical), and 96 more.